HMGA2 (high mobility group AT-hook 2)
Diseases named in the same sentence as HMGA2 in open-access papers (continued):
Sharing a sentence is not in itself a finding about the gene and the disease.
cancer (continued). "In this study, we found that overexpression of HMGA2 in cancer cells promoted macrophage recruitment and M2 polarization in TME by upregulating signal transducer and activator of transcription 3 (STAT3)-mediated CCL2 secretion in CRC, as evidenced by in vivo and in vitro experiments." (PMID 34976223, 2022). "Interestingly, HMGA1P6 and HMGA1P7 also regulate the expression of EZH2, HMGA2, and other cancer-related genes with a critical role in cancer progression by sponging miRNAs able to target these genes." (PMID 35804851, 2022). "HMGA2 increases cancer-cell proliferation by promoting cell-cycle entry and inhibiting apoptosis." (PMID 35328637, 2022). "The findings reported herein could also contribute to the understanding of the role of Hmga2 in cancer." (PMID 35918713, 2022). "Similar to other oncogenes, overexpression of HMGA2 may incur a survival advantage of human cancer cells." (PMID 35388973, 2022). "In addition, outside those mentioned, a group of transcription factors, which dysregulation has been widely associated with cancer phenotype was identified, including DEGs such as BCL6, DDIT3, GADD45A, HMGA2, and ID2." (PMID 35359411, 2022). "Altogether, our study shed light on miR-143ʹs anti-cancer biological functions in PTC progression through targeting HMGA2, suggesting that restoration of miR-143 could be a potential therapeutic approach for PTC treatment." (PMID 35213273, 2022). "HMGA2 has been shown to be a crucial regulator in cancers in a number of previous studies." (PMID 35213273, 2022). "Due to its role based on dynamic interaction with chromatin, Hmga2 has a pathogenic role in diverse tumors and has been mainly studied in a cancer context; however, whether Hmga2 has similar physiological functions in normal cells remains less explored." (PMID 35918713, 2022). "And while HMGA2 is uniquely expressed in early developmental stages before having trace detection in adult tissues, it is aberrantly re‐activated and overexpressed in cancers." (PMID 35388973, 2022). "HMGA2 correlates with the progression of many human cancers." (PMID 36180890, 2022). "Additionally, HMGA2 increases the expression of cancer stem cell markers, including CD44, Oct4, and Twist1." (PMID 33668453, 2021). "Previously, we showed that down regulation of HMGA2 expression could induce apoptosis in various types of cancer cells." (PMID 34356120, 2021). "The HMGA2 as target gene and protein was selected because recent studies have demonstrated that it has apoptotic effects and is frequently overexpressed by different cancers." (PMID 34356120, 2021). "HMGA2 is an oncogene upregulated in several cancers that stimulates proliferation and invasion." (PMID 34298609, 2021). "HMGA2 could be considered a novel target gene for the precision therapy due to its vital role in cancer and the specific expression characteristics in different developmental stages." (PMID 34513922, 2021). "HMGA2 is a transcription factor and may support cancer phenotypes by affecting the transcriptional landscape." (PMID 34680349, 2021). "Nevertheless, HMGA2 is re-expressed in many types of cancer, and it could manipulate tumorigenesis, metastasis, and relapse via participating in cell cycle, apoptosis, angiogenesis, epithelial–mesenchymal transition, and chemoresistance." (PMID 34513922, 2021). "Pan-cancer analysis showed that HMGA2 was upregulated in various types of cancer." (PMID 33731694, 2021). "HMGA2, by inhibiting autophagy, can decrease cancer drug resistance; however, most studies describe the significant role of HMGA2 in drug resistance by increasing cancer stem cell population, increasing DNA damage markers, and activating the Wnt-β catenin signaling pathway." (PMID 33668453, 2021). "Other studies showed that HMGA2 is overexpressed in lung, ovarian, breast, colorectal, pancreatic, gastric, prostate, bladder, tongue, pituitary, and thyroid cancers." (PMID 33668453, 2021).
cancer (continued). "Additionally, according to recent studies, the overexpression of HMGA2 has been discovered in many types of cancers and is involved in the initiation, development, and metastasis of cancer cells." (PMID 34356120, 2021). "HMGA2 increases cancer cell proliferation by promoting cell cycle entry and inhibiting cell death." (PMID 34115920, 2021). "Our results demonstrate that HMGA2 supports cancer hallmarks in TNBC and may represent a promising target for TNBC treatment." (PMID 34680349, 2021). "Interestingly, HMGA family proteins including HMGA2 have been suggested to impede DNA repair by downregulating the transcription of genes involved in various aspects of DNA repair processes in cancer cells." (PMID 32840881, 2021). "Moreover, HMGA2 supports a cancer stem cell phenotype and renders cancer cells resistant to chemotherapeutic agents." (PMID 33668453, 2021). "HMGA2 is a fetal-specific transcription factor that is re-expressed in many cancers." (PMID 33679795, 2021). "Moreover, HMGA2 is known to be involved in the DNA damage response and modulation of chemosensitivity in cancer cells in addition to its role in transcriptional regulation as a chromatin-associated protein." (PMID 34887387, 2021). "Several recent studies have unveiled therapeutic potential of HMGA2 silencing in various cancers." (PMID 33639654, 2021). "In addition to RNA-seq analyses, several studies that analyzed HMGA2 levels by IHC, Western blotting, and qRT-PCR found increased HMGA2 expression during cancer development." (PMID 33668453, 2021). "HMGA2 has been shown to be involved in cancer stemness in different types of cancers." (PMID 33668453, 2021). "HMGA2 suppression decreases expression of the cancer stem cell markers ALDH, SOX2, and Nanog." (PMID 33668453, 2021). "Importantly, in the vast majority of histochemical studies analyzing the relevance of HMGA2 for cancer development, progression and disease outcome, a solely nuclear presence of this protein was analyzed." (PMID 34302528, 2021). "HMGA2 exhibits high expression in various human carcinomas and is employed as a prognostic marker." (PMID 34703649, 2021). "Although further study is necessary, the regulation of TERT by HMGA2 might play a role in cancers that have disrupted TGF-β pathways, including HCC." (PMID 32577156, 2020). "HMGA2 can also mediate epithelial tumorigenesis by modulating apoptosis in cancer cells." (PMID 32365712, 2020). "HMGA2 can drive the cancer cell cycle forward by multiple mechanisms." (PMID 32850313, 2020). "Intriguingly, HMGA2 expression level always correlates with the degree of malignancy, metastasis, and a poor prognosis, suggesting that this protein is also a therapeutic target of anti-cancer and anti-metastasis drugs." (PMID 33139812, 2020). "In addition to its role in cancer, the let-7/HMGA2 axis was shown to regulate physiological processes, such as adipose, osteogenic, myeloerythroid and gliogenic differentiation, post-natal proliferation and ageing, and glucose metabolism." (PMID 31979076, 2020). "Recent studies suggested that several let-7 family members have diminished expression in cancer compared with normal tissues, and the effects of them on migration and invasiveness of cancer cells could be blocked by HMGA2, Lin28, or MMPs." (PMID 32432318, 2020). "High mobility group AT-Hook 2 (HMGA2) is a chromatin-binding protein, commonly expressed during embryogenesis, and is undetectable in the majority of adult tissues and linked to multiple types of cancer." (PMID 33168056, 2020). "Therefore, an urgent need remains to discover and develop potential therapeutic drugs to suppress the overexpression of HMGA2 in cancer patients." (PMID 32842685, 2020). "Additionally, significantly higher relative numbers of HMGA2-positve neoplastic cells were seen in VSCCs than in vulvar pre-cancers." (PMID 33374674, 2020).
cancer (continued). "Thus, HMGA2 also contribute in evading host immune response and continue cell proliferation, providing a survival advantage to cancer cells." (PMID 32752229, 2020). "(iii) Recently, it has been shown to bind HMGA2 and to potently inhibit DNA interactions, providing new insights into its anti-cancer and anti-metastasis functions, since the expression levels of HMGA proteins are associated with metastasis and poor prognosis for many cancer types." (PMID 33138093, 2020). "Additionally, inhibition of HMGA2 expression in GC cells reversed the cancer‐promoting effect of circ_0000267." (PMID 31845519, 2020). "The role played by HMGA2 in the formation of malignant tumors of epithelial origin is well known." (PMID 31660895, 2019). "MSI2, an RNA-binding protein, is a central regulator of the translation of cancer stem cell programmes and may be a target gene of HMGA2." (PMID 31053152, 2019). "One early work showed that Let-7a suppresses HMGA2 expression in cancer cells." (PMID 30934671, 2019). "Characterization of SMARCA4-depleted IPMN-PDAC cells revealed the presence of repressive histone marks on the promoters of high-mobility group AT-hook 2 (Hmga2) gene, mediator of aggressive cancer phenotype, and other genes whose expression was reduced in IPMN-PDA." (PMID 31769422, 2019). "HMGA2 gene involved in negative regulation of double-strand break repair via non-homologous end joining was found to be risen upon the treatment with 5a demonstrating its genotoxicity leading to the apoptotic death of cancer cells." (PMID 31842391, 2019). "HMGA2 is usually undetectable in normal adult somatic cells, but is expressed in embryonic tissues and embryonic stem (ES) cells, and re‐expressed in cancer (stem) cells." (PMID 30289618, 2019). "However, little has been reported regarding the relationship between HMGA2 expression and angiogenesis in malignant tumors." (PMID 31109142, 2019). "Furthermore, we show that HMGA2 significantly reduced genotoxic DNA damage in each tested cancer cell model during treatment with the TOP2A poison etoposide or the catalytic TOP2A inhibitor merbarone." (PMID 31271486, 2019). "Hence, we conclude that HMGA2 appears to have a general role as fork chaperone across various types of HU-treated cancer cells." (PMID 31067275, 2019). "HMGA2 has been widely known as an oncoprotein in cancer biology." (PMID 30934671, 2019). "One factor linked to poor clinical outcome in many cancers is the nonhistone chromatin‐binding protein high‐mobility group protein A2 (HMGA2)." (PMID 30289618, 2019). "In addition, HMGA2 expression can be detected in various cancers and is correlated with malignant degree and metastatic potential." (PMID 29507664, 2018). "In conclusion, HMGA2 overexpression indicates a worse prognosis and may serve as a prognostic predictor in cancer patients." (PMID 29416690, 2018). "The difference of HMGA2 expression in cancers and corresponding normal tissues in TCGA datasets." (PMID 29997523, 2018). "Since the high expression of HMGA2 could be potentially an indicator of poor prognosis in patients with certain cancers, HMGA2 was expected to be a new therapeutic biomarker in cancers." (PMID 29997523, 2018). "These cells, likely CSCs, express high levels of both HMGA1 and HMGA2; this might constitute an essential element of resistant cancer cells characterized by well-defined self-renewal and invasion factors." (PMID 29853899, 2018). "All these studies showed HMGA2 could play a key role in cancers, which supported it potential role as a biomarker for cancer therapy." (PMID 29997523, 2018). "To investigate if Hmga1 could functionally compensate for Hmga2, we stably knocked down Hmga1 in a cancer cell line generated from a KP172CT;Hmga2CK/CK lymph node metastasis." (PMID 30228296, 2018). "HMGA2 was detected in 21 types of cancers and corresponding normal tissues." (PMID 29997523, 2018). "In malignant tumors, HMGA2 overexpression has been reported in esophageal and lung cancers." (PMID 29487700, 2018).
cancer (continued). "Therefore, in this study, we explored the potential prognostic value of HMGA2 in human cancers by using meta-analysis based on published literatures and The Cancer Genome Atlas (TCGA) datasets." (PMID 29997523, 2018). "As a result, we found that high level of HMGA2 was related with poor OS in 13 types of cancers." (PMID 29997523, 2018). "Hmga1 and Hmga2 overlap in their expression in both human and murine PDAC, however knockdown of Hmga1 in Hmga2-deficient cancer cells also did not decrease metastatic ability." (PMID 30228296, 2018). "In this meta-analysis, we only sought to understand whether HMGA2 can be used as a prognostic biomarker in cancer patients." (PMID 29416690, 2018). "IGF1R and HMGA2 are important factors that are involved in cancer progression." (PMID 29507664, 2018). "High expression of HMGA2 has been detected in both epithelial and mesenchymal tissue of malignant tumors, and may promote tumorigenesis." (PMID 29416690, 2018). "Therefore, we conducted a meta-analysis of relevant studies to understand if HMGA2 has predictive prognostic potential in various cancers." (PMID 29416690, 2018). "Moreover, aberrant expression of HMGA2 promotes cancer invasion, metastasis, and epithelial-to-mesenchymal transition (EMT) by activating the transforming growth factor beta (TGFβ) and Wnt/β-catenin signaling pathways." (PMID 29416690, 2018). "Furthermore, miRNAs like miR-490-3p and miR-145 can inhibit cancer development and progression by direct regulation of HMGA2 expression." (PMID 29416690, 2018). "In order to validate the result of our meta-analysis, TCGA datasets were analyzed to explore whether HMGA2 could be involved in human cancers and affect patients’ survival." (PMID 29997523, 2018). "In addition, IGF1R and HMGA2 play an essential role in inducing epithelial-mesenchymal transition (EMT) in cancers." (PMID 29507664, 2018). "Because the compounds showed the ability to suppress expression of proliferation-associated genes such as HMGA2 and NMYC, we posited that #44 might affect the growth rate of cancer cell lines." (PMID 29162914, 2017). "In addition, Hmga2 plays a role in a variety of malignant tumors, including colorectal, breast, lung, prostate and bladder cancer as well as melanoma." (PMID 28415789, 2017). "Quantitative PCR of miR-93 and HMGA2 were done in fresh pancreatic samples of cancers and normal tissues, combining the opposite result of miR-93 and HMGA2 expression and function, we anticipated that miR-93 could work through regulating HMGA2 in PANC1 cells." (PMID 29245924, 2017). "High mobility group A2 (HMGA2) plays a crucial role in the development of cancer." (PMID 28522832, 2017). "In addition, genes potentially regulating lumican include HMGA2, an oncogene that is highly expressed in about 50% of carcinomas, which can downregulate LUM expression by directly binding its promotor region." (PMID 28481899, 2017). "Furthermore, highly expression of HMGA2 has been correlated with cancer proliferation, increased metastasis and poor prognosis in multiple types of cancer." (PMID 26818837, 2016). "Overexpression of HMGA2 has been reported in many kinds of human cancers." (PMID 26818837, 2016). "Our results identified HMGA2 as a novel negative modulator of the ATM dependent signaling pathway at telomeres and provided functional evidence for the additional telomere- and genome-protective role that cancer (stem) cells benefit from when they express HMGA2." (PMID 26799419, 2016). "Multi-functional HMGA2 has protective roles in ES and cancer cells." (PMID 26799419, 2016). "Notably, HMGA2 was highly expressed in CRC cell lines among the 9 different types of cancers, thus validating its specificity in CRC." (PMID 26893968, 2016).
cancer (continued). "Taken into consideration other known protective functions of HMGA2 in for example DNA damage repair and replication fork stabilization, our findings revealed an as yet less known protective mechanism facilitating enhanced chemoresistance of HMGA2+ cancer cells to the telomere-damaging drug KML-001." (PMID 26799419, 2016). "Thus, the HMGA2 protein is a promising biomarker for cancer detection as well as a potential molecular target in cancer therapy." (PMID 26893968, 2016). "Furthermore, the essential role of HMGA2 in cell proliferation and migration has been reported in various cancers." (PMID 26893968, 2016). "HMGA2 contributes to resistance against anticancer drugs in various cancer cell lines." (PMID 26893968, 2016). "We concluded that HMGA2 reduced telomere instability in cancer cells." (PMID 26799419, 2016). "The ability of HMGA2 in cancer (stem) cells to affect the stability of interphase telomeres and increase the resistance to telomere-targeting drugs identifies HMGA2 as an attractive novel therapeutic target to induce lethal telomere-mediated genomic instability in HMGA2+ cancer cells." (PMID 26799419, 2016). "In addition, HMGA2 is involved in maintaining cancer stem cells in the undifferentiated state, which are resistant to most of the cytotoxic drugs." (PMID 25946136, 2015). "In addition to regulating invasion and metastasis via a coding gene, HMGA2 also functions as a ceRNA to facilitate cancer metastasis in certain cancer types." (PMID 26123544, 2015). "HMGA1 and HMGA2 may have a role in NSCLC cancer progression also by regulating the expression of miRNAs." (PMID 25859543, 2015). "However, in various cancers, a high level of HMGA2 has been detected, and it is believed that HMGA2-related ROS production modifies redox regulation, leading to mold cellular phenotypes." (PMID 26273422, 2015). "This discrepancy might be due to low HMGA2 protein expression in the cancer tissue, and, then, low amount of circulating HMGA2." (PMID 25749380, 2015). "HMGA2 is expressed during early development but also in late stage or invasive cancer forms." (PMID 26998479, 2015). "Among these genes, HMGA2, CLDN1, TFPI2, KIAA0101 and EGR1 are cancer related genes according to Diseases Association Analysis and increased expression of EGR1 was confirmed by further semi-quantitative RT-PCR, quantitative RT-PCR and western blot in BCL6B re-expressed HepG2 and SNU449 cells." (PMID 25909168, 2015). "Additionally, let-7 represses the proliferation of cancer cells by directly targeting HMGA2, a protein which is frequently over-expressed in and promotes proliferation of many cancer types." (PMID 26123544, 2015). "Overexpression of HMGA1 and HMGA2 is a general feature of experimental and human malignancies and their overexpression is often correlated with aggressiveness, resistance to conventional anti-cancer therapies and poor prognosis." (PMID 25409711, 2014). "HMGA2+ cancer cells were shown to exhibit resistance against 4 of 11 anti-cancer drugs tested." (PMID 24723911, 2014). "Similarly, Hmga2 has been reported to be targeted by let-7 and miR-98 in cancer cells, both of which are up-regulated during myoblast differentiation." (PMID 24956113, 2014). "Finally, it has been outlined a novel gene-expression pathway in which an HMGA protein-coding gene, Hmga2, operates largely independently of its protein-coding function to promote cancer progression as a competing endogenous RNA." (PMID 25268743, 2014). "Indeed, HMGA2 exhibits dRP/AP site cleavage activity and protects cancer cells from DNA-damage-induced cytotoxicity during chemotherapy." (PMID 25409711, 2014). "Accordingly, HMGA2 expression increases as observed in embryonic stem cells and in several cancers." (PMID 25245141, 2014). "HMGA2 is a stem cell factor that promotes the invasiveness of cancer cells." (PMID 23846349, 2013). "The HMGA2 protein has been reported to be overexpressed in many types of cancer." (PMID 23599793, 2013).